IL10 (interleukin 10)
Diseases named in the same sentence as IL10 in open-access papers (continued):
Sharing a sentence is not in itself a finding about the gene and the disease.
tumor (continued). "In addition, potent self-protection from GBM and the presence of an immunosuppressive tumour environment comprised of Treg cells and marrow-derived stem cells (MDSCs) that produce IL-10 and TGF-β1 reduces the killing effects of DC-based vaccines on tumour cells." (PMID 28412740, 2017). "Since high levels of IL-10 were found in metastatic BC patients, it was proposed that higher serum amounts of this cytokine may contribute to immune surveillance impairment, favoring tumor development and progression." (PMID 29163540, 2017). "Furthermore, the mRNA information from 2013 TCGA cohort data included in the present study suggested that FGL2 expression was upregulated in ccRCC tissues and indicated that FGL2 expression was closely associated with the expression of tumour-promoting factors such as IL17 and IL-10 in ccRCC." (PMID 28978925, 2017). "Furthermore, high levels of TAM-derived IL-10 elicited T cell anergy in irradiated tumor." (PMID 28769933, 2017). "In addition to stromal cells and infiltrating immune cells, tumour cells also produce and secrete various types of cytokines, the most widely known of which are tumour necrosis factor-α24, transforming growth factor-β25 and IL-10 (refs 26, 27)." (PMID 28102193, 2017). "Moreover, the expression of IL-10 mRNA has been shown to correlate with the tumor grade." (PMID 28346397, 2017). "However others have found that IL-10 has potent anti-tumor effects." (PMID 29137411, 2017). "In addition, tumor-derived soluble mediators (e.g., IL-10, COX-1/2, VEGF, GM-CSF, IL-1β) can alter DC differentiation to preclude development of cells with antigen-presentation function and instead skew differentiation of DC precursors into immunosuppressive TAMs and MDSC." (PMID 28134800, 2017). "Temporary elimination of IL-10 could overcome the immunosuppressive tumour barrier in mice." (PMID 28154607, 2017). "However, IL10 may also stimulate the immune system thereby playing a role in tumor immune surveillance." (PMID 28594935, 2017). "Moreover, IL-10 blockade through antibody administration reduced the observed growth advantage compared to genetically identical tumors implanted into nulliparous hosts, demonstrating the presence of a tumor promotional immune response in the involuting gland." (PMID 28098775, 2017). "IL-10 mediates tumor immunosuppression and leads to the negative prognosis of tumor-bearing hosts, whose underlying mechanisms are that IL-10 could inhibit T cell proliferation and induce T cell to differentiate to the regulatory T cell phenotype." (PMID 28234961, 2017). "Furthermore, tumour-specific T-cells primed with these DCs released large amounts of cytokines such as IFN-γ, whose biological activity is associated with cytostatic/cytotoxic and antitumour mechanisms, and low levels of IL-10, which favour tumour growth." (PMID 26795765, 2016). "However, the influence of IL10 on tumor development is still controversial." (PMID 26956044, 2016). "Increased immune suppressive factors such as TGF-β, IL-10 and PD-L1 after C1 treatment implied that implementation of immunotherapy against these factors should occur as early as possible to improve the anti-tumor effects of chemotherapy in certain types of tumors." (PMID 27645787, 2016). "Thus, inhibition of either Nrp-1 or IL-10 can affect tumor-derived TGF-β1 levels." (PMID 27075020, 2016). "Studies in vitro and using tumor-bearing mice showed that c-kit inhibitors may induce a reduction of Treg cell number, decreasing consequently the expression of immunosuppressive cytokines (IL-10, TGFβ)." (PMID 28053982, 2016). "Therefore, we speculate that the simultaneous inhibition of IL10 and EGFR may achieve greater anti-tumor effects compared with the individual inhibition of IL10 or EGFR." (PMID 26956044, 2016).
tumor (continued). "Moreover, in response to upregulation of IFN-γ and IL-10, cells from tumour microenvironment like antigen presenting cells (APCs), tumour associated myeloid derived suppressor cells (MDSC), and M2 macrophages are able to produce indolamine 2,3-dioxygenase (IDO)." (PMID 26801617, 2016). "Some tumour cells may in fact produce immunosuppressive cytokines IL-10 and transforming growth factor-β (TGF-β), thus impairing the adaptive antitumour immune response, or eventually shift the immune response towards a Th2 response with less antitumour capacity." (PMID 27212807, 2016). "Therefore, we suggest that during chronic inflammation, TGFβ, IL-10, and retinoic acids may function together to maintain an immunosuppressive, tumor-promoting microenvironment." (PMID 26756215, 2016). "It is unclear whether CSF IL-10 is secreted by tumor cells or by cells within the tumor niche." (PMID 27924864, 2016). "In addition, the anti-tumor activity of IL10 has been addressed." (PMID 26956044, 2016). "Furthermore, IL-10 secretion could result in the deactivation of macrophages, which are important promoters of tumor progression and neovascularization; IL-10 secretion could also decrease angiogenesis by downregulating VEGF." (PMID 27445423, 2016). "However, during CRC development, Treg cells may switch their cytokine production from IL-10 to IL-17, which promotes tumor development." (PMID 27148488, 2016). "An alternatively activated macrophage phenotype is elicited by interleukin-4 (IL-4), IL-10, or transforming growth factor ß (TGFß), which are produced by helper 2 or regulatory T cells, tumor cells, or macrophages themselves during late stage immune responses and tumor cells." (PMID 26146544, 2015). "In summary, our data suggest that an increased in the frequency of CD14+CD169+ cells may be associated with the development and progression of CRC and is concomitant rise of both pro-tumor (M2-like, IL-10 producing) and anti-tumor (M1-like, IL-12 producing) monocytes and infiltrating macrophages." (PMID 26509874, 2015). "However, IL–10 was newly found to active anti-tumor immunity in tumor microenvironment." (PMID 26440936, 2015). "Since production of IL-12 p70 and IL-10 are key functional mediators of M1 and M2 cells, respectively, we also examined IL-12 p70 and IL-10 cytokines in the supernatants of co-culture between tumor cells and PBMC or purified monocytes, incubated with or without cetuximab." (PMID 26579227, 2015). "Indeed, nearly half of all tested NHL samples stained positive for IL-10 expression, and all patients that had detectable levels of IL-10 in ex vivo cultures also had elevated serum levels of IL-10, indicating that the tumor cells had been the major source of the cytokine." (PMID 25941795, 2015). "Since sAJ2 induce significant IL-10 secretion in untreated NK cells, and the levels substantially decrease when NK cells are activated with IL-2 or IL-2 + anti-CD16mAb, we aimed at determining whether such modulation also affects tumor differentiation." (PMID 26697005, 2015). "We postulate that the lymph node MGL-positive DC subsets might very effectively suppress immune responses through the secretion of high levels of immunosuppressive cytokines, such as IL-10, and the induction of regulatory T-cell responses, thereby supporting immune evasion of tumor cells." (PMID 26172302, 2015). "However, the persistent production of IL-10 by tumor cells and by tumor-promoted Tregs and macrophages may skew Th2 immunity in favor of IgG4 at early and late stages of disease manifestation." (PMID 26451312, 2015). "By engagement of their specific cellular receptors, cytokines such as IL-6 and IL-10 and VEGF activate the JAK2/STAT3 transduction pathway that promotes the transcription of genes encoding for proteins involved in PEL resistance to apoptosis and contributes to tumor survival." (PMID 25695042, 2015).
tumor (continued). "Our data suggest that an increase in the frequency of CD14+CD169+ cells may be associated with the development and progression of CRC and is concomitant rise of both, pro-tumor (M2-like, IL-10 producing) and anti-tumor (M1-like, IL-12 producing) monocytes and infiltrating macrophages." (PMID 26509874, 2015). "We have recently reported that B cells isolated from tumor-draining lymph nodes (TDLN) in a mouse breast tumor model were able to kill tumor cells in vitro and prevent metastases in vivo, and that B cells from IL-10-deficient mice were more potent killers of the tumor cells." (PMID 25852690, 2015). "Also we investigated correlations between tumor infiltrating T cells and serum IL-10." (PMID 26604855, 2015). "Moreover, VEGF increased IL-10 secretion of these cells and might therefore direct chemotaxis and immune modulation of T-cells in tumor tissues." (PMID 25254213, 2014). "At later stages of tumor progression, recruited monocytes differentiate into macrophage subpopulations with an overall more M2-like, wound healing or “trophic” phenotype (low IL-12 expression, high IL-10 expression, and low tumoricidal activity) that promotes tissue remodeling and angiogenesis." (PMID 24723924, 2014). "However, after the tumor was treated with three intratumoral injections of plasmid containing IL-12 cDNA, it showed a cytokine profile associated with Th1 with expression of IL-2, IL-12, and IFN-γ cytokines and reduced expression of IL-10, IL-4, and TGF-β1." (PMID 24808638, 2014). "Both IL-10 and HLA-G may be produced by tumor cells but also by tumor-infiltrating leucocytes." (PMID 24800261, 2014). "We investigated the possibility that cmvIL-10, a viral cytokine with homology to human IL-10 that is secreted from infected cells, could act in a paracrine manner to alter the tumor microenvironment, induce cell signaling, and increase the invasive potential of cancer cells." (PMID 24520416, 2014). "Thus IL-10 blockade holds promise to augment the anti-tumor effects of TLR agonists." (PMID 24624132, 2014). "In addition, mast cells can induce an immunosuppressive tumor microenvironment by directly enhancing regulatory T cell (Treg) function via mast cell-T cell contact, IL-10, tryptophan metabolism, amphiregulin production, or adenosine, or indirectly by inducing tolerogenic dendritic cells." (PMID 24931643, 2014). "Under oxidative stress, M-CSF may produce signals that are cumulative/synergistic with host mediators (e.g., low levels of histamine), facilitating tumor-directed expression of decoy receptors and immune suppressive factors (e.g., dTNFR, IL-5, IL-10, TGF-β, PGE2)." (PMID 24473090, 2014). "Indeed, several tumorigenic and angiogenic factors, such as VEGF and IL-10, released by the tumor in situ induce TIM-3 expression on TIDC surface, resulting in the suppression of innate immune responses to nucleic acids by binding to the damage-associated molecular pattern molecule, HMGB1." (PMID 23616948, 2013). "Thus, when given anti-CTLA-4 blocking antibodies the negative regulation mediated by CTLA4 is blocked, TGFβ and IL-10 remain in the postradiation tumor environment, and it is likely that these factors will continue to limit adaptive immune function despite CTLA4 blockade." (PMID 23653658, 2013). "Therefore, we tested the link between CD47 expression on tumor cell surface and IL-10 induction." (PMID 24073274, 2013). "Additionally, proper immune function may be disrupted by the tumor microenvironment through the direct impairment of mDCs by immunosuppressive molecules such as IL-10, TGF-β, VEGF-A, and CD200." (PMID 23606870, 2013). "Since it is clear that nearly all CD4 effector T cell subsets can potentially produce IL-10, it is conceivable that endogenous IL-10 (such as IL-10 derived from CD4 helper/effector T cells infiltrating sites of tumor growth) may exhibits both antitumor and pro-tumor activities." (PMID 23533029, 2013).
tumor (continued). "Thus, it is conceivable that IL-27 produced by tumor cells could contribute to IL-10 induction in an autocrine manner, in some cases." (PMID 24130734, 2013). "Interleukin 10 (IL-10) is a pleiotropic cytokine secreted by a wide array of immune cells, including monocytes, macrophages, T cells, dendritic cells (DC), B cells, natural killer (NK) cells, mast cells, neutrophilic and eosinophilic granulocytes, and by several tumor cells." (PMID 23663506, 2013). "Furthermore, IL10 might protect tumors by inhibiting cytotoxic T lymphocyte (CTL)-mediated tumor-specific cell lysis." (PMID 23460834, 2013). "Also, tumor or immune cells may respond with secretion of tumor-growth-promoting and immunosuppressive cytokines (e.g., IL10)." (PMID 24371445, 2013). "Furthermore, tumor cells may interfere with DC maturation through the secretion of IL-10, which results in the induction of antigen-specific anergy." (PMID 23606870, 2013). "Since the increase in Tregs is a general event in tumor-bearing mice which cannot explain the decreased proliferation capacity of lymphocytes from mice with high tumor burden, we hypothesized that immunosuppression could be correlated with the expression of IL-10 and TGF-β1." (PMID 22674057, 2012). "In addition to active T cell suppression at the tumor site, the expression of immune suppressive cytokines, such as interleukin 10 (IL-10), has also been related with an immune escape mechanism, partly because EBV-encoded LMP1 can induce IL-10." (PMID 22319542, 2012). "Since IL-10 has potent immunosuppressive and antiinflammatory properties and is produced by some cancers, it has been hypothesized that its production by tumor cells may contribute to the escape from immune surveillance; however, the results obtained in in vivo models are controversial." (PMID 22220169, 2012). "In addition, tumor cells can release immunosuppressive cytokines such as interleukin-10 (IL-10) or transforming growth factor-β1 (TGF-β1), which can not only inhibit anti-tumor immune responses but also increase proliferation of tumor cells in an auto- and paracrine manner." (PMID 22674057, 2012). "In the present study, we provide in vitro cellular and in vivo human tumor evidence to indicate that IL-10 mRNA expression levels may independently predict the survival and relapse rates in patients with HPV-positive OSCC, but not in those with HPV-negative OSCC." (PMID 23118878, 2012). "However, data concerning the role of IL-10 for tumor progression are also partially inconsistent." (PMID 22855687, 2012). "IL-10 has been shown to modulate apoptosis and suppress angiogenesis and enhance the production of tumor-toxic molecules (e.g., nitric oxide) and low levels of this cytokine could be favour tumor development." (PMID 23176085, 2012). "Taken together, these findings suggest that in addition to increased regulatory T cells, increased regulatory B cell numbers and activity may also contribute to the higher IL-10 levels and mediate the decreased protective immunity and increased tumor burden observed in HiAnx mice." (PMID 22558071, 2012). "Secretion of immunoregulatory Th2 cytokines and IL-10 are generally associated with the CD4+ subset of human and nonhuman primate NKT lymphocytes, whereas DN NKT tend to have more effector properties in terms of Th1 cytokine secretion, cytotoxicity and greater anti-tumor efficacy." (PMID 23028326, 2012). "However, in mouse models, the effect of IL-10 on the anti-tumour immune response is controversial." (PMID 22220169, 2012). "As the EBERs are believed to possess antiapoptotic activities, as well as the ability to induce the expression of IL-10, which may promote tumor cell growth and survival, it has been suggested that these RNAs may play an essential role in the oncogenesis of Burkitt lymphoma." (PMID 22319542, 2012).
tumor (continued). "In addition to rDCs being producers of PGE2 and IL-10, the release of these mediators by stromal cells has also been implicated in their generation, with splenic endothelial-produced IL-10 and tumor stroma-derived PGE2 playing a role in the induction of rDC populations." (PMID 22934098, 2012). "Moreover, in BL, the production of IL10 by tumor cells might stimulate intratumoral macrophages to differentiate and to promote B cell survival." (PMID 23029361, 2012). "TLRs exist in almost immunosuppressive cells and recent study showed that tumor cell-derived HMGB1 might suppress naturally acquired CD8 T cell-dependent antitumor immunity via enhancing Treg to produce IL-10, which is necessary for Treg-mediated immune suppression." (PMID 22747650, 2012). "Therefore, it is possible that systemic injection of Pam2 lipopeptides in our system may induce IL-10 from NK cells and suppress anti-tumor response in vivo." (PMID 21533081, 2011). "TAM with high IL-10 expression level may tune inflammatory responses and adaptive Th2 immunity, exhibit anti-inflammatory and tissue remodeling functions and thereby, to favor tumor progression." (PMID 21595995, 2011). "Thus, while the tumor changes the environment in the bladder, as shown by the increase in IFNγ and IL10, it too is changed by the activity of the immune cells recruited to the bladder which selectively destroy the immunogenic cells and thus encourage the survival of less immunogenic cells." (PMID 22013484, 2011). "Finally, the pleiotropic cytokine IL-10, which may exert tumor-promoting activity or considerable antitumor effects, at low and high concentrations, respectively, was detected at lower amounts in HER2- patients." (PMID 22112244, 2011). "Besides IL10, there may be other immunosuppressive mechanisms involved in the interplay between the immune system and the tumor cells." (PMID 22013484, 2011). "However, other authors demonstrated that lack of IL-10 expression by the tumor was associated with a worse survival in patients with stage I NSCLC." (PMID 21595995, 2011). "Bergmann and co-authors used cell culture techniques with weak doses of IL-2, IL-10, and IL-15 to show that the tumor microenvironment generated Tr1 cells with a phenotype distinct from nTregs and that these cells abolished autologous responders proliferation via the secretion of IL-10 and TGF-β." (PMID 21437225, 2010). "In addition, the levels of IL-10 and IL-13 were also increased in tumor after BMMC injection." (PMID 20111717, 2010). "Other causes include secretion of inhibitory substances e.g. IL-10, TGF-β, abnormal T-lymphocyte signal transduction and expression of Fas ligand, which may enable tumour cells to induce apoptosis in Fas expressing tumour infiltrating lymphocytes." (PMID 20181099, 2010). "There is evidence that pDCs arelocated in several types of tumors: head and neck cancer, ovarian cancer,primary melanoma cancer, and breast cancer.Secreted factors by tumor cells may inhibit pDCs function, such as TGFβ,vascular endothelial growth factor β (VEGFβ), and IL-10." (PMID 19190769, 2008). "In addition, tumor cells can induce IL-10 in the tumor environment." (PMID 16478542, 2006). "However, resection of the primary tumour did not appear to be associated with significant normalisation of circulating concentrations of C-reactive protein, interleukin-6 or interleukin-10." (PMID 17003778, 2006). "Despite their heterogeneity, all Tregs subsets potently suppress antitumor immunity through secretion of TGF-β, IL-10, and IL-35, supporting tissue homeostasis, and in the TME tumor reinforcing the immunosuppressive tone." (PMID 41601669, 2026). "ELISA results demonstrated that circPVT1 knockdown reduced tumor cell secretion of IL4, IL10, and TGFβ, thereby promoting macrophage polarization toward the M1 phenotype." (PMID 42094010, 2026).